IL6 (interleukin 6)
Diseases named in the same sentence as IL6 in open-access papers (continued):
Sharing a sentence is not in itself a finding about the gene and the disease.
colon carcinoma (continued). "Only still differentiated colon carcinoma cells are responsive to the growth stimulatory action of IL-6." (PMID 18205904, 2008). "Evidence is provided that in human colon cancer, undifferentiated tumour cells are the main source of IL-6." (PMID 18205904, 2008). "At present, we are unaware of any means by which IL-6 secretion from undifferentiated colon cancer cells can be effectively suppressed." (PMID 18205904, 2008). "IL-6 can be released from tumour infiltrating leukocytes, but is produced to a large extent by tumour cells themselves: In human colon cancer, IL-6 expression parallels tumour progression, reaching a maximum in high grade cancerous lesions." (PMID 18205904, 2008). "How effective IL-6 is in promoting progression and metastatic spread of colon cancer, depends not only on the extent of basal but, importantly, on the extent of inducible IL-6 expression at certain stages of tumour development." (PMID 18205904, 2008). "A positive correlation between miR-21 and Interleukin-6 (IL-6) expression was discovered in colon cancer; miR-21 levels could be enhanced by oncogenic signaling IL-6, leading to NF-kB activation, which maintain an inflammatory and a pro-carcinogenic state." (PMID 41303164, 2025). "MUC2 plays an important role in IL-6 signaling during colon cancer metastasis." (PMID 40859234, 2025). "Gastrin‐SiO2 microspheres (20 mg kg−1 day−1, 80 μL/10 g), administered by gavage (10–20 s), did not affect the mRNA expression of inflammatory factors (TNFα, MCP‐1, MCP‐2, IL‐1β, and IL‐6) in the intestine and colon cancer promoting markers in the serum (CEA, CA199, and PSA)." (PMID 39950948, 2025). "It reduces the levels of pro-inflammatory cytokines (e.g., IL-6 and TNF-α) and pro-carcinogenic cytokines (TGF-β1, TNF-β, and CXCL12) which exerts an inhibitory effect on pancreatic cancer associated fibroblasts (CAF) and colon cancer (HCT 116) cells." (PMID 40490812, 2025). "By modeling specific biological pathways, such as IL-6 signaling, which is implicated in both IBD and colon cancer, the study underscores the potential of digital twins to improve precision medicine in oncology by enhancing the accuracy of treatment predictions." (PMID 40429568, 2025). "A study showed that Bifidobacterium longum isolated from breast milk can relieve colon cancer by significantly increasing the concentration of IL-1β, an anti-inflammatory factor, and decreasing the concentration of IL-6, a pro-inflammatory factor in colon cancer model mice." (PMID 38540948, 2024). "IL-6 overexpression in colon cancer is pro-tumorigenic by promoting defects in the DNA MMR system." (PMID 38975417, 2024). "Notably, WNT2high CAFs stimulated EC migration, fostering colon cancer progression by inducing the WNT2-dependent upregulation of pro-angiogenic factors such as IL6, G-CSF, and PGF." (PMID 38453816, 2024). "Furthermore, in colon cancer, CAFs expressing IL6 have been identified to produce VEGF and instigate angiogenesis." (PMID 38453816, 2024). "Thus, the serum titer of autoantibodies was inversely correlated with the serum concentration of IL-6 in colon cancer, indicating that a high titer of autoantibodies blocks the activity of IL-6IF." (PMID 39518029, 2024). "The current results demonstrated elevated levels for TNF-α (376.2 ± 20.9 vs. 94.8 ± 18.3) and NFκB (3,287.7 ± 264.7 vs. 724.5 ± 79.1) and for the downstream products IL-1β (446.9 ± 23.3 vs. 85.25 ± 13.5) and IL-6 (258.0 ± 34.7 vs. 20.7 ± 9.8) in the colon cancer group versus the saline group." (PMID 38645563, 2024). "The promotion of CT26 colon cancer cell proliferation induced by IL-6 was examined first." (PMID 38504172, 2024). "Induction of colon cancer by AOM caused elevation of IL-6, IL-12p70, and TNF-α in normal diet+AOM compared to normal diet control." (PMID 39845239, 2024).
colon carcinoma (continued). "Moreover, in cannabidiol-treated mice, the IL-6 and IL-8 serum levels were significantly lower than the untreated mice with colon cancer, indicating that CBD decreases the cancer-induced inflammation." (PMID 38755733, 2024). "Previous investigations from our research team demonstrated that the combination of FLCWK with 5‐FU suppressed the proliferation and induced apoptosis in colon cancer cells by modulating the IL‐6/STAT3 signalling pathway, resulting in the inhibition of colon tumour growth in CAC mice." (PMID 39495702, 2024). "Gr-1+ MDSCs are a source of IL-6 in a murine colon cancer model." (PMID 39338937, 2024). "Consistently, a study using IL-6-deficient mice bearing a murine colon cancer cell line found that the lack of IL-6 enhances the induction of effector T cells and inhibits tumorigenesis." (PMID 38022654, 2023). "In addition, indolimines enhance IL6 expression in a colonic tumor cell line in combination with cytokine treatment." (PMID 37755265, 2023). "Furthermore, macrophage-induced IL-6 favored the migration and invasion of colon cancer cell via WNT/β-catenin in a STAT3/ERK-dependent manner." (PMID 36980226, 2023). "Based on the tendency of the CB2−/− mice to develop spontaneous colon cancer, we hypothesized that high IL-6 in the periphery leads to upregulation of MDSCs." (PMID 36835468, 2023). "For example, supplementation with SCFAs for kidney and liver diseases, inflammatory bowel disease, and colon cancer reduced the pro-inflammatory mediators, tumor necrosis factor alpha (TNFα), interleukin-6 (IL-6), and C-reactive protein, as well as disease progression." (PMID 37432606, 2023). "Overexpression miR-155-5p in M2 macrophage-derived exosomes promotes CRC cell proliferation, antigenic capacity, enhanced CD3 T cell and IFN-γ T cell proliferation, and significantly reduces IL-6 expression levels, leading to colon cancer the immune escape and induction of tumor formation." (PMID 38188683, 2023). "Therefore, the growth rate of both types of colon cancer cells was increased in the presence of IL-6." (PMID 36900505, 2023). "Furthermore, an in vitro study also demonstrated that the addition of TNF-α, IL-1β, and IL-6 factors to the conditioned medium of activated macrophages significantly triggered the proliferation and immigration of human colon carcinoma cells." (PMID 36559282, 2022). "In addition, activation of IL-6-STAT3 signaling contributes fibroblasts to their conversion into CAFs in normal gastric fibroblasts, and IL-6 enhances the proliferation of human colon carcinoma cells in vitro." (PMID 36016615, 2022). "Furthermore, the upregulation of IL-6 and GM-CSF was observed in colon cancer tissue versus normal tissue according to the Oncomine database." (PMID 35022523, 2022). "It has been shown that the lack of IL-6 in the tumour microenvironment of IL-6 deficient mice inhibited tumour growth of colon cancer cells; however, blocking IL-6 by anti-IL-6 antibody alone did not block tumour growth of PDAC." (PMID 36077801, 2022). "Expression of miR-21 and miR-29b is stimulated in colon tumor cells in the presence of IL-6." (PMID 35410210, 2022). "We subsequently tested if the altered expression in IL-6 and IL-1β would affect the tumor microenvironment and modify signaling in colon cancer cells by treating COLO205 cells with the supernatant from THP1 transfected cells combined with regular growth media (1:1) followed by cell growth for 72 h." (PMID 35499706, 2022). "Since SIRT1 positively regulates expression of IL‐6 and IL‐8 that play crucial roles in proliferation of colon cancer cells, we speculate that SIRT1 may partly promote the colon cancer cell growth and migration through production of these cytokines." (PMID 34826187, 2022). "IL-6 has been shown to promote the growth of colon-cancer-derived cells in vitro." (PMID 35326545, 2022).
colon carcinoma (continued). "However, in vivo findings provided experimental evidence for the synergistic and beneficial therapeutic effects of combined IL-6/ PD-L1 blockade in the CT26 colon cancer model." (PMID 36428508, 2022). "Moreover, the IL6/JAK/STAT3 pathway has been found to upregulate CXCL1, CXCL2, CXCL3, and CXCL11 in patients with colon cancer, which was associated with prognosis." (PMID 35468892, 2022). "In colon cancer, aberrant IL-6/STAT/SOCS3 signaling may be critical for CRC development and progression." (PMID 36158694, 2022). "Specifically, these shared pathways with IBD were linked to inflammation (TNF, IL-1A, IL-1B, NFkB, IL-6) and growth (TREM1, TGFB1), while other pathways shared with colon cancer were associated with colorectal metastatic signaling, growth (TREM1, NFkB and HMGB1) and inflammation (IL-8, IL-6)." (PMID 35323693, 2022). "Similarly, iCAFs are found to affect the process of epithelial–mesenchymal transformation in colon cancer cells by secreting IL-6 in previous studies." (PMID 35401551, 2022). "Likewise, we detected the colon cancer prognostic biomarker CXCL8 and its associated pro-inflammatory cytokines (IL1-β, TNF-α, IFN-γ and IL-6) in the serum of mice in each group." (PMID 35922850, 2022). "IL-6 has been shown to contribute to STAT3 activation in colon cancer." (PMID 36207761, 2022). "Taken together, these observations suggest that SIRT1 stabilized through phosphorylation on serine 27 exerts oncogenic effects at least partly through deacetylation‐dependent activation of Snail and subsequent transcription of IL‐6 and IL‐8 in human colon cancer cells." (PMID 34826187, 2022). "Furthermore, IL-6 is known to stimulate tumor escape from immune surveillance induced by cell-in-cell structures that were formed by lymphocytes and colon cancer cells." (PMID 33718596, 2021). "Based on this data, we speculated whether ZC3H12B affected the development of colon cancer by regulating IL-6." (PMID 33718596, 2021). "Therefore in the present work we evaluated an effect of transferrin—a necessary ferroptotic factor on IL-6 synthesis and release by colon cancer cells." (PMID 34681200, 2021). "Although the exact mechanism is unknown, studies in colon cancer models have shown that the overexpression of RKIP inhibits IL-6-, Jak-, or Src kinase-mediated phosphorylation of STAT3 known to be necessary for its activation." (PMID 34944867, 2021). "Recent studies have reported an increase in interleukin-6 (IL-6) and soluble interleukin-6 receptor (sIL-6R) levels in the sera of patients affected by colon cancer that correlate with the tumor size, suggesting a potential role for IL-6 in colon cancer progression." (PMID 33923292, 2021). "Interestingly, CCL20 secreting TAMs were induced via IL-6-regulated macrophage polarization in a mouse model of colon cancer; in which, CCL20 promoted cancer progression by recruiting CCR6+ lymphocytes." (PMID 34439098, 2021). "The stromal fibroblasts, obtained from colon cancer, produced prominent amounts of IL-6." (PMID 34631734, 2021). "Since several reports demonstrated that IL-6 enhances the migration ability and invasiveness of gastric and colon cancer cells, we investigated the effect of the treatment with rIL-6 on either migration or invasive ability in human primary T88 and T93 colon cancer cells." (PMID 34885656, 2021). "Moreover, another critical finding in the current study was that the transfer of miR-155-5p into colon cancer cells via M2 macrophage-derived exosomes to target ZC3H12B diminished the expression levels of IL-6." (PMID 33718596, 2021). "Furthermore, we demonstrated that LPEs behave as anti-inflammatory agents able to prevent or counteract the invasiveness of colon cancer cells, mainly by the inhibition of IL-6-dependent effects induced on MMP-2 activity and expression." (PMID 34885656, 2021).
colon carcinoma (continued). "Similar to the differential microbiota results, systemic inflammatory cytokines were positively correlated with the colon cancer process, and key protein levels of LPS, IL-6, IL-22 and IL-17A in mouse serum were significantly higher after modelling than in the sham group (p < 0.01 or p < 0.01)." (PMID 34531745, 2021). "The activation of IL-6 trans-signaling by metalloproteinases has been described during colon cancer progression and metastasis, involving a shift from membrane-bound interleukin-6 receptor (IL-6R) expression on the tumor cell surface toward the release of soluble IL-6R." (PMID 33923292, 2021). "Furthermore, significant positive correlations of CBX4 with STAT1 and IL-6R/STAT3 were observed, and the activation of STAT1 and IL-6/STAT3 signaling has been reported to promote immunosuppression in the TME of colon cancer." (PMID 34222240, 2021). "Collectively, our findings indicated that M2 macrophage-derived exosomal miR-155-5p can potentially promote the immune escape of colon cancer by impairing ZC3H12B-mediated IL-6 stability reduction, thereby promoting the occurrence and development of colon cancer." (PMID 33718596, 2021). "However, it has been shown that the colon cancer cell line HTM-29 cannot secrete IL-6 upon IL-1β- or TNF-α-stimulation, because these cytokines do not lead to NF-κB activation here." (PMID 34671021, 2021). "The significant increase in the level of interleukin such as IL-1, IL-4, IL-6 was recorded in colon cancer patients (17.26 ± 2.49 pg/ml, 32.18 ± 1.45 pg/ml, 28.26 ± 1.88 pg/ml) as compared to controls (6.35 ± 1.07 pg/ml, 21.25 ± 2.18 pg/ml, 9.58 ± 3.33 pg/ml), respectively." (PMID 34096454, 2021). "In this study, we have demonstrated that circulating NF-κB, TNF-α, IL-6, PTX-3, PCT, and CRP levels in breast and colon cancer were significantly higher than in control groups and NF-κB levels were positively correlated with IL-6, PTX-3, PCT, and CRP in all patients." (PMID 33776564, 2021). "Based on in vitro studies, β estrogen receptor could down-regulate pro-inflammatory cytokines, such as IL-6, to play a colon cancer-prevention effect." (PMID 31963221, 2020). "This indicates that the inhibition of the activity of cytokines such as IL6 and GM‐CSF could effectively improve the sensitivity of radiotherapy and chemotherapy to colon cancer cells." (PMID 31650683, 2020). "Furthermore, AdoMet was able to prevent the inflammation-induced colon cancer by azoxymethane and dextran sulfate sodium in Balb/c mice through inhibition of β-catenin, IL-6 signaling, pro-inflammatory, pro-growth, and proliferation pathways." (PMID 33374288, 2020). "In the present study, the results showed that JK5G treatment could significantly inhibit the growth of colon tumors, as well as the levels of cytokines in serum, such as IL-2, IL-6, and TNF-α." (PMID 33178591, 2020). "In addition, a lower survival ratio was strongly associated with a higher expression of LRG5 in patients with metastatic colon cancer and IL-6 in recurrent colon cancer." (PMID 32560222, 2020). "In the present study, we investigated posttranslational regulatory mechanisms downstream of the IL-6/STAT3/FRA1 inflammatory signaling axis that mediate colon cancer stemness and malignancy and explored novel combinatorial therapeutic approaches to target CRC stem and bulk cells." (PMID 30804456, 2019). "In addition, biofilm has been associated with decreased expression of E-cadherin on colonic epithelial cell, an over activation of IL-6 and Stat3 in epithelial cell, all these mechanisms are involved in colon cancer." (PMID 31662752, 2019). "In our study, tumor epithelial cells isolated from stage II primary colon cancers, mRNA transcript expression of IL6 and IL11, their cognate receptors, and gp130 were detected although it was the expression levels of gp130 which determined cellular sensitivity to IL6 and IL11 stimulation." (PMID 30885958, 2019).
colon carcinoma (continued). "As an example, patients with colon cancer demonstrated a high level of IL-6." (PMID 31295906, 2019). "We concluded from these data that in colon cancer, IL-6 trans-signaling apparently acted downstream of the EGF-R and blockade of IL-6 trans-signaling might represent a novel therapeutic window for patients resistant to anti-EGF-R antibodies." (PMID 31694340, 2019). "Both IL-6 and IL-8 are proinflammatory cytokines regulated by NF-κB transcription factor, a link between inflammation and cancer; and NF-κB activation has been also shown in colon cancer." (PMID 31662752, 2019). "In human colon tumor tissues, it was shown that the expression and activity of ADAM17 was significantly increased as compared with normal tissue, underlining an important role of ADAM17 in mediating the IL-6 trans-signaling response via the sIL-6R." (PMID 31694340, 2019). "The in vivo study showed that HBD could significantly reduce the mortality of mice and control the incidence and size of colonic tumors by inhibiting the IL-6/STAT3 signaling pathway." (PMID 30832202, 2019). "Besides, anti-IL-6 antibody abolished the migration and invasion of colon cancer cells induced by IL-6-activated pathway." (PMID 30175384, 2018). "IL-6 is known to be involved in the metastasis in several cancers, and IL-6 may enhance cancer cell migration to promote metastasis in colon cancer." (PMID 30308035, 2018). "Similarly, everolimus, a specific mTOR inhibitor, reduced IL-6 levels and alleviated the cachectic phenotype of CT-26 colon cancer bearing mice in which IL-6 is the main cachectic driver." (PMID 30061533, 2018). "Furthermore, pathway analysis revealed that the metformin-predicted group was characterized by decreased interleukin (IL)-6 pathway signaling, epithelial–mesenchymal transition, and colon cancer metastatic signaling." (PMID 30308035, 2018). "Moreover, there was also a decrease in levels of inflammatory cytokines TNF-α, IL-1β, IL-6, and IL-17A in the sera or colon tissues of Trim27−/− mice, which was consistent with the decreased inflammatory cell infiltrations in colon tumors of Trim27−/− mice." (PMID 30143645, 2018). "Another possibility for a tumor-suppressing role of circulating TGF-β1 could be the inhibition of IL-6 trans-signalling in colon cancer." (PMID 30071009, 2018). "In conclusion, our study shows that MK2 activity in colon tumors and colon tumor-associated macrophages is a critical regulator of not only IL-1β, IL-6, and TNF-α but also MMM, which has not previously been reported." (PMID 30298062, 2018). "In colonic tumors, lack of vanin-1 is associated to higher levels of PPARg and to a reduction in IL-6 production and STAT3 activation." (PMID 28448444, 2017). "Notably, MMP-1 (~250-fold, P < 0.01) and IL-6 responsive BCLXL mRNAs were greatly increased after treatment with IL-6 (18 h) in SW480 colon cancer cells under conditions of high (10%) serum." (PMID 28819304, 2017). "Importantly, increased IL-6 expression levels were also detected in colonic tumors induced by AOM-DSS treatment in Sdc1-KO, as compared to wt mice." (PMID 28350804, 2017). "We hypothesized that IL-6 induces invasion and metastasis of primary colon cancer through the epithelial-mesenchymal transition (EMT) process." (PMID 28725043, 2017). "Importantly, induction of IL-6 / STAT3 axis was also detected in colonic tumors derived from Sdc1 KO mice." (PMID 28350804, 2017). "MUC2 suppression enhanced IL-6 secretion and tumor growth in a colon cancer animal model." (PMID 28725043, 2017). "In our study, we found that IL-6 secreted by colon cancer cells modulates tumor metastasis." (PMID 28784136, 2017). "Furthermore, both LS174T and SW480 colon cancer cell lines were confirmed to be responsive to IL-6: evidenced by the induction of IL-6 responsive genes, and expression of IL-6 receptors (gp130 & IL-6R)." (PMID 28819304, 2017).